FMR1 (fragile X messenger ribonucleoprotein 1)
Description:
Multifunctional polyribosome-associated RNA-binding protein that plays a central role in neuronal development and synaptic plasticity through the regulation of alternative mRNA splicing, mRNA stability, mRNA dendritic transport and postsynaptic local protein synthesis of target mRNAs. Acts as an mRNA regulator by mediating formation of some phase-separated membraneless compartment: undergoes liquid-liquid phase separation upon binding to target mRNAs, leading to assemble mRNAs into cytoplasmic ribonucleoprotein granules that concentrate mRNAs with associated regulatory factors. Plays a role in the alternative splicing of its own mRNA. Stabilizes the scaffolding postsynaptic density protein DLG4/PSD-95 and the myelin basic protein (MBP) mRNAs in hippocampal neurons and glial cells, respectively; this stabilization is further increased in response to metabotropic glutamate receptor (mGluR) stimulation (By similarity). Plays a role in selective delivery of a subset of dendritic mRNAs to synaptic sites in response to mGluR activation in a kinesin-dependent manner (By similarity). Undergoes liquid-liquid phase separation following phosphorylation and interaction with CAPRIN1, promoting formation of cytoplasmic ribonucleoprotein granules that concentrate mRNAs with factors that inhibit translation and mediate deadenylation of target mRNAs. Acts as a repressor of mRNA translation in synaptic regions by mediating formation of neuronal ribonucleoprotein granules and promoting recruitmtent of EIF4EBP2. Plays a role as a repressor of mRNA translation during the transport of dendritic mRNAs to postsynaptic dendritic spines. Component of the CYFIP1-EIF4E-FMR1 complex which blocks cap-dependent mRNA translation initiation (By similarity). Represses mRNA translation by stalling ribosomal translocation during elongation (By similarity). Reports are contradictory with regards to its ability to mediate translation inhibition of MBP mRNA in oligodendrocytes. Also involved in the recruitment of the RNA helicase MOV10 to a subset of mRNAs and hence regulates microRNA (miRNA)-mediated translational repression by AGO2. Facilitates the assembly of miRNAs on specific target mRNAs. Also plays a role as an activator of mRNA translation of a subset of dendritic mRNAs at synapses. In response to mGluR stimulation, FMR1-target mRNAs are rapidly derepressed, allowing for local translation at synapses (By similarity). Binds to a large subset of dendritic mRNAs that encode a myriad of proteins involved in pre- and postsynaptic functions. Binds to 5'-ACU[GU]-3' and/or 5'-[AU]GGA-3' RNA consensus sequences within mRNA targets, mainly at coding sequence (CDS) and 3'-untranslated region (UTR) and less frequently at 5'-UTR. Binds to intramolecular G-quadruplex structures in the 5'- or 3'-UTRs of mRNA targets. Binds to G-quadruplex structures in the 3'-UTR of its own mRNA. Also binds to RNA ligands harboring a kissing complex (kc) structure; this binding may mediate the association of FMR1 with polyribosomes. Binds mRNAs containing U-rich target sequences. Binds to a triple stem-loop RNA structure, called Sod1 stem loop interacting with FMRP (SoSLIP), in the 5'-UTR region of superoxide dismutase SOD1 mRNA. Binds to the dendritic, small non-coding brain cytoplasmic RNA 1 (BC1); which may increase the association of the CYFIP1-EIF4E-FMR1 complex to FMR1 target mRNAs at synapses (By similarity). Plays a role in mRNA nuclear export. Specifically recognizes and binds a subset of N6-methyladenosine (m6A)- containing mRNAs, promoting their nuclear export in a XPO1/CRM1-dependent manner. Together with export factor NXF2, is involved in the regulation of the NXF1 mRNA stability in neurons (By similarity). Associates with export factor NXF1 mRNA-containing ribonucleoprotein particles (mRNPs) in a NXF2-dependent manner (By similarity). Binds to a subset of miRNAs in the brain. May associate with nascent transcripts in a nuclear protein NXF1-dependent manner. In vitro, binds to RNA homomer; preferentially on poly(G) and to a lesser extent on poly(U), but not on poly(A) or poly(C). Moreover, plays a role in the modulation of the sodium-activated potassium channel KCNT1 gating activity. Negatively regulates the voltage-dependent calcium channel current density in soma and presynaptic terminals of dorsal root ganglion (DRG) neurons, and hence regulates synaptic vesicle exocytosis (By similarity). Modulates the voltage-dependent calcium channel CACNA1B expression at the plasma membrane by targeting the channels for proteasomal degradation (By similarity). Plays a role in regulation of MAP1B-dependent microtubule dynamics during neuronal development (By similarity). Has been shown to play a translation-independent role in the modulation of presynaptic action potential (AP) duration and neurotransmitter release via large-conductance calcium-activated potassium (BK) channels in hippocampal and cortical excitatory neurons. May be involved in the control of DNA damage response (DDR) mechanisms through the regulation of ATR-dependent signaling pathways such as histone H2AX/H2A.x and BRCA1 phosphorylations. Forms a cytoplasmic messenger ribonucleoprotein (mRNP) network by packaging long mRNAs, serving as a scaffold that recruits proteins and signaling molecules. This network facilitates signaling reactions by maintaining proximity between kinases and substrates. [Isoform 10]: Binds to RNA homomer; preferentially on poly(G) and to a lesser extent on poly(U), but not on poly(A) or poly(C). May bind to RNA in Cajal bodies. [Isoform 6]: Binds to RNA homomer; preferentially on poly(G) and to a lesser extent on poly(U), but not on poly(A) or poly(C). May bind to RNA in Cajal bodies. (Microbial infection) Acts as a positive regulator of influenza A virus (IAV) replication. Required for the assembly and nuclear export of the viral ribonucleoprotein (vRNP) components.
Synonyms: FMRP; FRAXA; MGC87458; POF; POF1
Tractability: Small molecule: a structure with a bound ligand is known. Antibody: UniProt places it where antibodies can reach, with medium confidence; its Gene Ontology location is reachable by antibodies, with medium confidence. PROTAC: UniProt records ubiquitination sites on it; ubiquitination databases record sites on it; its protein half-life has been measured.
Gene: Protein-coding gene on chromosome X (147,911,858 to 147,951,125, forward strand). Ensembl gene ENSG00000102081.
Subcellular location: Cytoplasm, Cytoplasmic ribonucleoprotein granule; Cytoplasm, Stress granule; Cytoplasm; Perikaryon; Cytoplasm, perinuclear region; Cell projection, neuron projection; Cell projection, axon; Cell projection, dendrite; Cell projection, dendritic spine; Synapse, synaptosome; Cell projection, growth cone; Cell projection, filopodium tip; Synapse; Postsynaptic cell membrane; Presynaptic cell membrane; Nucleus; Nucleus, nucleolus; Chromosome, centromere; Chromosome; Cell membrane; and 5 more
Subcellular location (Human Protein Atlas): Cytosol
Gene Ontology:
Molecular function: G-quadruplex RNA binding; histone H3 reader activity; identical protein binding; miRNA binding; molecular condensate scaffold activity; mRNA 3'-UTR binding; mRNA 5'-UTR binding; mRNA binding; N6-methyladenosine-containing RNA reader activity; poly(A) binding; poly(G) binding; poly(U) RNA binding; protein binding; protein heterodimerization activity; protein homodimerization activity; ribosome binding; RNA binding; RNA stem-loop binding; RNA strand annealing activity; sequence-specific mRNA binding; signaling adaptor activity; siRNA binding; translation initiation factor binding; translation repressor activity; transmembrane transporter binding; and 6 more
Biological process: cellular response to virus; DNA repair; host-mediated perturbation of viral RNA genome replication; membraneless organelle assembly; mRNA export from nucleus; negative regulation of miRNA-mediated gene silencing; negative regulation of translation; positive regulation of intracellular transport of viral material; positive regulation of miRNA-mediated gene silencing; positive regulation of receptor internalization; positive regulation of translation; regulation of alternative mRNA splicing, via spliceosome; regulation of dendritic spine development; regulation of filopodium assembly; regulation of neuronal action potential; stress granule assembly; animal organ development; glutamate receptor signaling pathway; mRNA transport; negative regulation of cytoplasmic translation; negative regulation of long-term synaptic depression; negative regulation of synaptic vesicle exocytosis; negative regulation of translational initiation; negative regulation of voltage-gated calcium channel activity; positive regulation of dendritic spine development; and 11 more
Cellular component: cell projection; cytoplasm; cytoplasmic ribonucleoprotein granule; cytoplasmic stress granule; cytosol; excitatory synapse; growth cone; intracellular membraneless organelle; membrane; neuron projection; neuronal ribonucleoprotein granule; nucleolus; nucleoplasm; nucleus; perikaryon; perinuclear region of cytoplasm; ribonucleoprotein complex; SMN complex; translation repressor complex; axon; axon terminus; chromocenter; chromosome; dendrite; dendritic filopodium; and 13 more
Gene-disease validity (ClinGen):
ClinGen rates the evidence that FMR1 causes each of these diseases.
fragile X syndrome (X-linked): Definitive. A genetic syndrome caused by mutations in the FMR1 gene which is responsible for the expression of the fragile X mental retardation 1 protein.
Homologues: Orthologues: chimpanzee FMR1 (99% identical), macaque FMR1 (99% identical), rabbit FMR1 (98% identical), pig FMR1 (98% identical), dog FMR1 (97% identical), mouse Fmr1 (96% identical), guinea pig FMR1 (94% identical), rat Fmr1 (94% identical), tropical clawed frog fmr1 (79% identical), zebrafish fmr1 (66% identical), Drosophila melanogaster Fmr1 (36% identical). Paralogues in human: FXR1 (57% identical), FXR2 (53% identical).
Diseases named in the same sentence as FMR1 in open-access papers:
FMR1 is named in the same sentence as 291 diseases in open-access papers, as found by Europe PMC text mining. Sharing a sentence is not in itself a finding about the gene and the disease. The quoted sentences say what the papers report.
fragile X syndrome (1,132 papers, 2006 to 2026). "Fragile X Syndrome (FXS) is a genetic disorder caused by increased CGG repeats within the Fragile X Messenger Ribonucleoprotein 1 (FMR1) gene that results in gene silencing and deficiency of FMR protein (FMRP) expression." (PMID 41525319, 2026). "For example, a mutation in FMR1 (Ile304Asn) identified in a patient with Fragile X syndrome led to decreased FMR RNA-binding activity." (PMID 41160875, 2026). "Fragile X Syndrome (FXS) is a genetic disorder caused by increased CGG repeats in the Fragile X Messenger Ribonucleoprotein 1 (FMR1) gene which encodes an RNA-binding protein that can alter mRNA processing, translation and stability." (PMID 41525319, 2026). "Fragile X syndrome (FXS) is a neurodevelopmental disorder caused by silencing of the FMR1 gene and loss of fragile X messenger ribonucleoprotein (FMRP), leading to synaptic dysfunction and prominent sensory processing abnormalities." (PMID 41888648, 2026). "Full mutations at FMR1 exceeding 200 CGG repeats lead to Fragile X Syndrome (FXS), a neurodevelopmental disorder caused by FMR1 hypermethylation and subsequent gene silencing, associated with intellectual disability, autism, and seizures." (PMID 41278766, 2025). "There was high concordance with repeat size estimates from conventional PCR-based methods although larger repeats such as FMR1 associated with fragile X syndrome and DMPK repeat expansion associated with myotonic dystrophy type 1 were underestimated." (PMID 39349043, 2025). "Many studies suggest that the FMR1 gene is about 6 % of POF cases.The FMR1 gene is involved in three different syndromes: fragile X syndrome, POF, andFragile X-associated tremor/ataxia syndrome (FXTAS) at an older age." (PMID 39835794, 2025). "In this context, CGG triplet expansions, associated with Fragile X Syndrome, have been linked to histone hypoacetylation and chromatin condensation, which contributes to the inactivation of FMR1 gene." (PMID 41035523, 2025). "The Fragile X Mental Retardation 1 (FMR1) gene, well-known for its association with Fragile X syndrome (FXS), a neurodevelopmental disorder, has traditionally been studied in the context of the central nervous system." (PMID 40563420, 2025). "Mutations in FMR1 cause Fragile X syndrome, which is the most common monogenic cause associated with ASD." (PMID 40519825, 2025). "For example, expansion of a trinucleotide repeat within the FMR1 5′UTR can cause a loss of function resulting in Fragile X-syndrome." (PMID 39912332, 2025). "FMR1 is a crucial gene involved in Fragile X syndrome, a genetic disorder associated with intellectual disability and FXPOI." (PMID 40244008, 2025). "An example is the silencing of the FMR1 gene in the Fragile X syndrome by R-loops formed by FMR1 RNA and FMR1 DNA: in this case, the R-loops are associated with histone repressive marks." (PMID 40352720, 2025). "The FMR1 gene, whose mutation is causally associated with fragile X syndrome, is also considered the primary known genetic cause of autism." (PMID 40519825, 2025). "Fragile X syndrome is caused by increased CGG repeats in the fragile X messenger ribonucleoprotein (FMR1) gene promoter, which leads to its silencing." (PMID 41243972, 2025). "Certain short tandem repeats (STRs) are associated with neurologic diseases, including fragile X syndrome, which is associated with FMR1 and often co‐occurs with ASD." (PMID 39610113, 2025). "This conservation extends to disease mechanisms, as mutations in FMR1—such as R138Q in the KH0 domain—are linked to Fragile X Syndrome (FXS)." (PMID 40588021, 2025).
fragile X syndrome (continued). "FMR1 gene analysis was conducted in 39 children and adolescents (32%), identifying two cases consistent with Fragile X syndrome (FXS) (diagnostic yield: 5%, in selected cases)." (PMID 41527628, 2025). "FMR1 disorders range from premutation (PM) to full mutation (FM) leading to fragile X syndrome (FXS), fragile X-associated tremor/ataxia syndrome (FXTAS), and fragile X-associated primary ovarian insufficiency (FXPOI), according to number of repetitions." (PMID 40275386, 2025). "Fragile X syndrome (FXS) is primarily caused by the expansion of CGG repeats in the 5’ untranslated region of the FMR1 gene." (PMID 40940631, 2025). "Another downregulated gene is the RNA-methylating enzyme METTL3, previously reported to be regulated by the β-catenin/WNT signaling pathway in an autism mouse model, as well as by the FMR1 gene, causative of the autistic Fragile X syndrome." (PMID 38637827, 2024). "Loss-of-function mutations in the FMR1 gene leading to fragile X syndrome (FXS) are the most frequent monogenetic cause (6–8%) of ASD in humans, with a general prevalence of ASD at ∼2% of children." (PMID 38627066, 2024). "Fragile X syndrome is the most common cause of inherited intellectual disability caused by hypermethylation of the Fmr1 gene, which impairs translation of Fragile X messenger ribonucleoprotein 1 protein (FMRP)." (PMID 38911597, 2024). "Transcriptional silencing of the Fragile X messenger ribonucleoprotein 1 (Fmr1) gene encoding the Fragile X Messenger Ribonucleoprotein causes fragile X syndrome, the most common monogenic cause of ASD characterized by intellectual and language disabilities." (PMID 38716113, 2024). "One example is CGG triplet expansion in the fragile X messenger ribonucleoprotein 1 (FMR1) gene causing fragile X syndrome." (PMID 37581649, 2024). "For instance, the FMR1 gene has been associated with fragile X syndrome, a genetic condition that presents with ASD-like symptoms." (PMID 38672454, 2024). "Fragile X syndrome (FXS) is an X-linked inherited intellectual disability caused by >200 CGG repeats mutation (‘full mutation’) in the fragile X messenger ribonucleoprotein 1 gene (FMR1)." (PMID 39465205, 2024). "This includes fragile X syndrome, a monogenetic disorder caused by the loss of the Fmr1 gene of the X chromosome that leads to social behaviour problems, learning difficulties, and developmental delays, collectively known as ASD." (PMID 39770443, 2024). "PV in FMR1 causing fragile X syndrome, the most common cause of intellectual disability especially in males, cannot be detected with exome sequencing data." (PMID 38167091, 2024). "There were 488 women with fragile X syndrome—FMR1 gene detection, and 6 patients (1.2%) had FMR1 gene mutation." (PMID 38562051, 2024). "While the majority of ASD aetiology is unclear, the most common single-gene cause of ASD is believed to be due to the silencing of the fragile X messenger ribonucleoprotein 1 (FMR1) gene resulting in Fragile X syndrome (5% of ASD cases)." (PMID 39411003, 2024). "Fragile X syndrome (FXS) is a genetic disorder caused by a mutation in the fragile X messenger ribonucleoprotein 1 (FMR1) gene and known to be a leading cause of inherited intellectual disability globally." (PMID 38927619, 2024). "We recently observed such CC-DEGs when comparing transcriptomes from pools of embryos either wild-type or homozygous for a loss-of-function mutation in the zebrafish gene fmr1 (orthologous to the human FMR1 gene mutated in Fragile X Syndrome)." (PMID 38346074, 2024). "Long CGG repeat expansion in the 5′ non-coding region of the FMR1 gene are associated with fragile X syndrome (FXS), a common hereditary form of intellectual disability and autism." (PMID 38391932, 2024). "Fragile X syndrome arises from a mutation in the Fragile X Messenger Ribonucleoprotein 1 (FMR1) gene on the X chromosome." (PMID 39095891, 2024).